MCL1 (MCL1 apoptosis regulator, BCL2 family member)
Diseases named in the same sentence as MCL1 in open-access papers (continued):
Sharing a sentence is not in itself a finding about the gene and the disease.
cancer (continued). "Wogonin, a natural plant-based flavone was shown to target CDK9 activity, in an ATP-competitive manner, resulting in lower pS2 and MCL-1 levels and increased apoptosis in CLL and multiple other cancer entities." (PMID 34062779, 2021). "MCL1, an antiapoptotic BCL-2 family member that is essential for cell survival, is highly amplified in many types of cancer." (PMID 34156978, 2021). "SRSF1 is known to be involved in the expression of many cancer promoting genes as well as in the expression of pro-apoptotic isoforms of Bcl-x, RON, and MCL-1." (PMID 34944633, 2021). "By both competitively inhibiting BH3 binding at the groove, and promoting degradation in cells, the small molecules dramatically reduce MCL‐1 activity in treated cells, promoting apoptosis in MCL‐1 dependent cancer cell lines." (PMID 32961017, 2021). "We demonstrated that ANO1-5f resulted in reduction of cancer cell viability and ANO1 protein levels in ANO1HIGH cells, as well as decrease in the expression of MCL1." (PMID 33803266, 2021). "As knockdown of MCL1 drives cells from HR to the rapid, error-prone NHEJ, the combination of MCL1 and PARP inhibition was highlighted as a novel pathway to expose cancer cells to a targeted vulnerability." (PMID 34475520, 2021). "FBXW7 is a critical tumor suppressor that regulates proteasome-mediated degradation of various oncoproteins, such as cyclin E, c-Myc, Mcl-1, mTOR, Jun, Notch and AURKA in human cancer." (PMID 33450701, 2021). "In this study, we have shown the potential markers for sensitivity of cancer cells to Mcl-1 inhibition and effective combinations of agents to overcome a resistance to BH3 mimetics to Mcl-1." (PMID 35008345, 2021). "Our findings confirm the contribution of MCL1 to nab-PTX resistance in ESCC, consistent with other cancer types." (PMID 34638252, 2021). "For example, it is well established that most cancer cells overexpress anti-apoptotic proteins BCL-2, BCL-xL or else MCL-1." (PMID 33920941, 2021). "Myeloid cell leukemia-1 gene (MCL1) and B-cell leukemia/lymphoma-xl (BCL-xl) are cell apoptosis regulators and express aberrantly in cancer, which plays an important role in chemoresistance." (PMID 34722892, 2021). "Myeloid cell leukemia 1(MCL1), an anti-apoptotic protein that belongs to the BCL-2 family, often keeps a high expression in many cancers during oncogenesis." (PMID 33225418, 2021). "Given that cancer cell growth or apoptosis is influenced by the expression levels of anti‐apoptotic proteins, such as the family of Bcl‐2 and IAPs,31, 32 we next investigated whether dasatinib affects the expression levels of Bcl‐2, Mcl‐1 and XIAP in YD‐38 cells." (PMID 34318593, 2021). "MCL-1 protein levels as well as BCL-XL have been demonstrated to influence sensitivity to ABT-199 and ABT-263 in other cancers types." (PMID 33494434, 2021). "As shown, these survival genes (BIRC5, MCL1, XIAP) were significantly increased expressions in the cancer tissues, while the apoptotic gene (CAS9) was reduced compared to the normal tissues from healthy individuals." (PMID 34307149, 2021). "H3K4me3 is also able to recruit spliceosome components to promote the exclusion of exon 2 from the MCL1 (myeloid cell leukemia 1) pre-mRNA, resulting in the expression of the MCL1S isoform, which induces cancer cell apoptosis." (PMID 33407694, 2021). "Taken together, our findings reveal that the inhibition of BMI-1 induces Mcl-1 destabilization through downregulation of DUB3, resulting in the induction of cancer cell death." (PMID 34576269, 2021). "Strikingly, in three out of 25 tested cancer types, survival of the high scoring group (high activation of FGF signalling and high expression of BCL-2 or MCL-1) was significantly decreased when compared to the low scoring group." (PMID 34772930, 2021). "In certain cancer types, we found a correlation between FGF-signalling, BCL-2 and MCL-1 expression and poorer patient prognosis." (PMID 34772930, 2021).
cancer (continued). "Using this approach, we identified several cancer types that displayed a correlation between FGF activation and BCL-2 and/or MCL-1 expression." (PMID 34772930, 2021). "Lucanthone induced DUB3-dependent Mcl-1 downregulation and miR-216a-5p-mediated DR5 upregulation, resulted in the enhancement to TRAIL sensitivity in cancer." (PMID 35008442, 2021). "Alternative splicing of Bcl-2 family genes Mcl-1 and Bcl-x, a-raf gene, fructokinase (KHK) gene, RON gene, and EWS-FLI1 transcripts by hnRNP F/H are reported to contribute to various cancer cells proliferation, metastasis, and apoptosis-resistance." (PMID 31863069, 2020). "The anti-apoptotic proteins BCL-2, MCL-1 and BCL-xL prevent MOMP via direct interactions with the pro-apoptotic proteins and have been shown to protect cancer cells from stress stimuli induced by chemotherapies." (PMID 33080792, 2020). "The activated PI3K/AKT/mTOR pathway can decrease the BCL-2 homology domain (BH3) mimetic effectiveness in cancer cells by upregulating anti-apoptotic BCL-2 family members, such as myeloid cell leukemia-1 (MCL-1) and B-cell lymphoma-extra large (BCL-XL)." (PMID 32131492, 2020). "Targeting of MCL-1 with a small molecule inhibitor (MI-233) blocked MCL-1-mediated HR DNA repair and thereby sensitized cancer cells to treatment induced replication stress." (PMID 33308268, 2020). "Combination of MCL-1 inhibitors with inhibitors of EGFR, MEK, or B-RAF showed potent antitumor activity in various preclinical models of cancer." (PMID 32722518, 2020). "Based on the prominent role of MCL-1 in human cancer, previous studies focussed on NOXA mainly to address its role as a target for cancer therapy." (PMID 32913203, 2020). "Collectively, we showed that magnolol sensitized cancer cells to TRAIL-induced apoptosis through ATF4-dependent DR5 upregulation, proteasome-mediated Mcl-1 downregulation and lysosome-mediated c-FLIP downregulation." (PMID 33050112, 2020). "Suppression of the anti-apoptotic proteins MCL1, BCL2, and BCL2L1 by BH3 mimetics has been well-known to induce the BAX/BAK-modulated mitochondrial death pathway of pro-apoptotic proteins in cancer cells." (PMID 32486166, 2020). "Whereas the majority of previous results deal with the turn-over of NOXA and the alteration of UPS in cancer, recent studies explored a novel view about the fate of NOXA/MCL-1 protein complex on mitochondria." (PMID 32913203, 2020). "Magnolol sensitized cancer cells to TRAIL-induced apoptosis through ATF4-dependent DR5 upregulation and proteasome-mediated Mcl-1 and c-FLIP downregulation." (PMID 33050112, 2020). "Copy number variations have been detected in the anti‐apoptotic members MCL1 and BCL2L1 across 26 human cancers, including gynaecologic cancers." (PMID 32419250, 2020). "Among these, BH3 mimetics are small molecules developed to inhibit pro-survival proteins (BCL-2, BCL-xL, MCL-1), unleashing BAX/BAK to promote MOMP and apoptosis onset in otherwise aberrantly surviving cancer cells." (PMID 32722518, 2020). "Since CLK inhibitor decreases the expression levels of Mcl-1 and S6K, CLK inhibitors are viable therapeutic options for the treatment of sunitinib-resistant cancers." (PMID 33064779, 2020). "This generates a dependence on MCL-1 in treated cancer cells, that can be therapeutically overcome by sequential inhibition of BRAF and MCL-1 in preclinical studies." (PMID 32722518, 2020). "Chemoresistance is a severe concern regarding the poor prognosis of cancer patients, and MCL1, an antiapoptotic BCL-2 family member, has become a popular target for cancer treatment due to its important effects." (PMID 32699213, 2020). "This made the anti-apoptotic protein an attractive cancer therapeutic target and several classes of agents, including CDK9 and direct MCL1 inhibitors, are now being tested in clinical trials [reviewed in refs: 61,62]." (PMID 32645016, 2020).
cancer (continued). "MCL1 impedes BAK/BAX-dependent apoptosis, and S63845 inhibits the binding of BAK and BAX to MCL1, resulting in cancer cell death." (PMID 32152266, 2020). "The augmented level of c-FLIP, Bcl-2 and Mcl-1 has been noted in NSCLC, posing present and future challenges in cancer therapy." (PMID 32069989, 2020). "As USP9X inhibition has been linked to apoptosis and prevention of drug resistance in malignancies through Mcl-1 degradation, WP1130 is thought to target a Bcr-Abl-/Mcl-1-specific pathway as a USP inhibitor, suggesting a capacity for cancer treatment." (PMID 32272746, 2020). "Several reports associate resistance to ABT-737 with high expression levels of MCL-1 and it has therefore been proposed that the inhibition of MCL-1 increases the anti-cancer effect of ABT-737." (PMID 31973201, 2020). "Inhibition of HSP90A with AUY922 robustly dampened AKT phosphorylation level and expression of the effectors in NANOG signaling, such as MCL-1, Cyclin A, and TCL1A across all tested cancer cells." (PMID 31992715, 2020). "We previously identified the MCL1 H-score, an anti-apoptotic member of the BCL2 family of apoptosis-regulating proteins, as an independent factor for cancer death in patients with cervical AC receiving CRT." (PMID 32527042, 2020). "Many anti-apoptotic proteins in the intrinsic apoptosis pathway, such as Bcl-2, B cell lymphoma-extra large (Bcl-xL), Mcl-1, and some IAP proteins, are overexpressed in human cancers." (PMID 33172112, 2020). "Because many cancer cells escape cell death by activating the anti-apoptotic pathway such as via the upregulation of Mcl-1, BH3 mimetics are used for cancer treatment to inhibit anti-apoptotic activity and promote cell death." (PMID 32471110, 2020). "The anti-cancer effects of WP1130 rely primarily on the inhibition of USP9X, and inhibition of USP9X by WP1130 induces downregulation of Mcl-1 and XIAP expression." (PMID 30862047, 2019). "The independent inhibition of multiple antiapoptotic gene products (survivin, Mcl-1, XIAP, cIAP2) is important as various combinations of these proteins are known to be simultaneously overexpressed in various stages of resistant cancers." (PMID 31439015, 2019). "MCL-1 is a member of the BCL-2 superfamily of apoptosis regulators, and it is one of the most frequently amplified genes in cancers." (PMID 31864341, 2019). "Cancer cells avoid apoptosis through various strategies that include increased expression of pro-survival proteins such as BCL-2, BCL-XL, or MCL-1." (PMID 31399555, 2019). "One such route frequently utilized by cancer cells is upregulation of the antiapoptotic BCL2 family proteins, including BCL2, MCL1, BCL2A1, and BCLxL." (PMID 30635584, 2019). "Affymetrix expression data of 71 of the (untreated) corresponding tumors were available to study the relationship between stromal presence, MCL-1 expression and sensitivity to ABT-737 in luminal cancers (Left)." (PMID 30631150, 2019). "High levels of anti-apoptotic MCL-1 and other members of the BCL-2 family (eg, BCL-2, BCL-xL) have been shown to contribute not only to the development of some forms of cancer, but also to providing them with survival advantages and chemotherapy resistance." (PMID 30815228, 2019). "Many anti-apoptotic proteins such as C-FLIP, MCL-1, and XIAP inhibit apoptosis through disruption of extrinsic/intrinsic apoptotic pathways in cancers." (PMID 31238539, 2019). "CDK2 inhibition can also be highly effective in inducing apoptosis as it down-regulates the MCL-1 protein, leading to synergy with BH3 mimetics in various cancer cell line models." (PMID 30720718, 2019). "Further, MCL1, a potent oncoproteins which belongs to the BCL-2 family is known to be inhibited miR-29b in cancer cells." (PMID 31340494, 2019). "Our previous studies have shown that CDKI‐73 induced apoptosis by targeting short‐lived pro‐survival mRNA, such as Mcl‐1, XIAP and Bcl‐2 in cancer cells." (PMID 31398271, 2019).
cancer (continued). "This study demonstrates that targeting both BCL-xL and MCL-1 is required to optimally inhibit BCL-family pro-survival molecules in HNSCC, and co-inhibition is synergistic in HNSCC cancer cells." (PMID 30728900, 2019). "Since MCL1, PTBP1, and miR-101 are central regulators of various cellular processes, all have valuable therapeutic potentials in anti-cancer treatment." (PMID 29748555, 2018). "In this section, we will review the miRNA-mediated post-transcriptional control of BCL2, MCL1, BCLxL, BCLW, and BFL1, and their identified roles in cancer biology and anti-cancer drug response." (PMID 29361709, 2018). "Aberrant increases in the level of anti-apoptotic Bcl-2 proteins such as BCL-2, MCL-1 or BCL-XL prevents apoptosis, this both promotes cancer and allows resistance to cancer therapy-induced cell killing." (PMID 29339815, 2018). "Selective targeting of MCL-1 (A1210477), BCL-2 (ABT-199), and BCL-xL (WEHI-539) revealed that hyperosmotic stress apparently enforced BCL-xL addiction of cancer cells to survive." (PMID 29706657, 2018). "It is clinically important that the cancer stem cell-targeting compound PTC596 decreased MCL-1 expression levels and antagonized ibrutinib-induced increase in MCL-1 expression." (PMID 29983879, 2018). "In cancer development, MCL-1 is upregulated, preventing apoptosis; thus, downregulation or knockdown of MCL-1 contributes to apoptosis, as reported in several cancers." (PMID 29899871, 2018). "Critically, CDK9-mediated transcription of MCL-1 and MYC plays an important role in growth and survival of cancer cells, and dysregulation of this component of the CDK9 pathway is prominent in a number of hematologic malignancies." (PMID 29471852, 2018). "With these limitations in mind, we set out to address the following questions: What are the dependencies of diverse human cancers with respect to BCL-2, BCL-XL, MCL-1, and their combinations?" (PMID 30158527, 2018). "MCL1, a pro-survival BCL-2 related protein with rapid turnover rate, is often dysregulated in cancers." (PMID 29335437, 2018). "PEITC sensitized cancer cells to cisplatin in biliary tract through PEITC-induced depletion of overall GSH, which facilitated Mcl-1 glutathionylation, promoted Mcl-1 degradation and resensitized cells to cisplatin." (PMID 27911871, 2017). "ATF5 also promotes survival of malignant cells by stimulating expression of anti-apoptotic B-cell leukemia-2 (BCL2) and myeloid cell leukemia sequence-1 (MCL1), a BCL2 family member, indicating a prosurvival role in cancer." (PMID 28860159, 2017). "Recently, Studies have reported that both c-met and MCL-1 can be regulated by miRNAs, and the miRNAs-c-met/MCL-1 axis determined the drug sensitivity to several cancers." (PMID 29312559, 2017). "In this work, we for the first time used a combination of computer modelling and biological assays, to investigate the fundamental Mcl-1-PUMA interactions and to seek potential small molecules with high anti-cancer activity and safety." (PMID 28903337, 2017). "ABT-263 increases Mcl-1 stability, but the inhibition of ERK, JNK or Akt activity can sensitise the cancer cells to ABT-263." (PMID 28464919, 2017). "MCL1 is an anti-apoptotic protein in BCL2 family, and amplifies frequently in multiple human cancers." (PMID 29072681, 2017). "Particular GFRN members can upregulate anti-apoptotic proteins such as BCL-2, BCL-XL, and MCL-1 and downregulate pro-apoptotic proteins such as BAD, BAX, and BIM, all of which contribute to apoptosis evasion and resistance to cancer treatments in patients." (PMID 28446242, 2017). "Potent and selective small-molecule MCL-1 inhibitors A-1210477 synergizes with the BCL-2 and BCL-xL inhibitor ABT-263 to kill a variety of cancer cell lines." (PMID 28659182, 2017).
cancer (continued). "In many cancer cells, PUMA-dependent apoptosis is typically blocked by the elevated expression of myeloid cell leukemia-1 (Mcl-1, one of the most frequently overexpressed anti-apoptotic proteins) and the resulting deregulation of the Mcl-1-PUMA interaction." (PMID 28903337, 2017). "Recently, a group showed a novel Mcl-1 inhibitor S63845, which inhibits Mcl-1 via binding to the BH3-binding groove of Mcl-1, was able to potently kill various cancer cells both in vitro and in vivo." (PMID 29383093, 2017). "Recent identification of cell-permeable, selective inhibitors of BCL-2, BCL-XL and MCL-1, further facilitates the determination of the BCL-2 family dependency of cancer cells." (PMID 26954718, 2016). "The discovery of maritoclax was exciting because the molecule binds specifically with Mcl-1 and increases the efficacy of ABT-737 in various cancer cells lines; however, further pharmacokinetic studies are needed to translate this agent to clinic." (PMID 26927133, 2016). "Malignant tumors frequently exhibited poor expression of miR-32, whose targets include NRAS, PI3K and notably, MCL-1." (PMID 27846237, 2016). "Transfection of miR-26b mimics suppressed Mcl-1 expression in HCC cells and sensitized the cancer cells to TRAIL (tumor necrosis factor-related apoptosis-inducing ligand) cytotoxicity." (PMID 26078955, 2015). "To confirm Mcl-1 as a general target of UNBS1450, we tested this compound on other human cancer cell lines (lung, prostate, breast, blood and nerve tissue)." (PMID 26068790, 2015). "This recently reported small molecule is more potent in inhibiting BCL-XL than navitoclax but shows negligible activity against BCL-2 or MCL-1, thus making it an excellent tool for dissecting BCL-XL cancer biology." (PMID 26134786, 2015). "Here we introduce a series of direct, potent and selective MCL-1 inhibitors that demonstrate clear on-target cellular activity, disrupting MCL-1–BIM protein complexes and triggering apoptosis in cancer cell lines shown to rely on MCL-1 for survival." (PMID 25590800, 2015). "The most potent MCL-1 inhibitor can engage the binding groove of MCL-1 in computational docking experiments, and it shows antagonizing activity in cancer cells." (PMID 25970783, 2015). "Two independent groups have also shown that Mcl-1 phosphorylation at Thr92 and Thr163, stimulated by TPA-induced ERK activation, stabilizes Mcl-1 in some cancer cell lines." (PMID 24814761, 2014). "Others reporting results and our previous data have shown that ABT-263 upregulates Mcl-1 in HCC cells, which is the crucial reason for ABT-263 resistance in cancer therapy." (PMID 24779770, 2014). "Thus, MAPKs and Mcl-1 may be potential molecular targets for apoptotic cell death in cancer cells." (PMID 24348795, 2014). "Our results provide the first evidence that, in aggressive EC cells, miR-101 governs multiple malignant phenotypes including proliferation, migration, invasion and cancer stemness, at least partly via downregulating the expression of EZH2, MCL-1 and FOS." (PMID 25153722, 2014). "An NF-кB overactivation has been observed in cancer, and this leads to upregulation of the BCL-XL, SURVIVN and MCL-1 genes, and this increase resistance to apoptosis in tumor cells." (PMID 24495648, 2014). "Our in vitro cell growth data showed that BM-1197 is about 8-times more effective than ABT-263 in MEF cells with Mcl-1 deletion and is 5-26-fold more potent than ABT-263 in 4 most sensitive SCLC cancer cell lines." (PMID 24901320, 2014). "Previous reports have shown that ABT-263 upregulates Mcl-1 in various cancer cells, which contributes to ABT-263 resistance in cancer therapy." (PMID 24779770, 2014).